RNU6-87P (RNA, U6 small nuclear 87, pseudogene)
Gene: Small nuclear RNA gene on chromosome 12 (51,014,134 to 51,014,241, reverse strand). Ensembl gene ENSG00000272028.
Homologues: Orthologues: chimpanzee U6 (99% identical), macaque U6 (97% identical). Paralogues in human: RNU6-11P (89% identical), RNU6-235P (89% identical), RNU6-28P (89% identical), RNU6-37P (89% identical), RNU6-774P (89% identical), RNU6-16P (88% identical), RNU6-38P (88% identical), RNU6-1 (87% identical), RNU6-144P (87% identical), RNU6-2 (87% identical), RNU6-39P (87% identical), RNU6-3P (87% identical), and 1288 more.